CYFIP1 (cytoplasmic FMR1 interacting protein 1)
Diseases named in the same sentence as CYFIP1 in open-access papers (continued):
Sharing a sentence is not in itself a finding about the gene and the disease.
fragile X syndrome (23 papers, 2008 to 2025). A genetic syndrome caused by mutations in the FMR1 gene which is responsible for the expression of the fragile X mental retardation 1 protein. "CYFIP1 is highly expressed in the perinuclear region and synaptosomes, is part of the ribonucleoprotein complex, and is associated with Fragile X syndrome and ASD." (PMID 38172840, 2024). "Through the CYFIP1 protein, the fragile X syndrome protein represses activity-dependent translation, and thus implicated in fragile X syndrome." (PMID 32384786, 2020). "Findings in the deletion overlap with previous white matter differences reported in fragile X syndrome patients, suggesting common pathogenic mechanisms derived from disruptions of cytoplasmic CYFIP1-fragile X mental retardation protein complexes." (PMID 30583851, 2019). "The CYFIP1 gene encodes a protein associated with fragile X syndrome." (PMID 36901699, 2023). "For example, findings in the deletion group overlapped with more white matter differences previously reported in the fragile X syndrome suggesting common pathogenic mechanisms derived from disruptions of the cytoplasmic CYFIP1–fragile X mental retardation protein complexes." (PMID 36901699, 2023). "Haploinsufficiency of CYFIP1 can cause similar symptoms to fragile X syndrome in mice." (PMID 30909440, 2019). "The CYFIP1 gene encodes a protein product that interacts with FMRP, the protein coded by the FMR1 gene causing fragile X syndrome." (PMID 35787815, 2022). "CYFIP1 interacts with the Fragile X mental retardation protein (FMRP, encoded by the FMR1 gene), whose absence causes Fragile X syndrome, and with the translation initiation factor eIF4E." (PMID 28183735, 2017). "The CYFIP1 protein interacts with the fragile X mental retardation protein (the absence of which causes fragile X syndrome)." (PMID 32066678, 2020). "The CYFIP1 gene is known to interact with the WAVE regulatory complex and proteins from two genes: RAC1, disruption of which causes an autosomal dominant form of intellectual disability, and FMR1, the causative gene for fragile X syndrome." (PMID 30909440, 2019). "Additionally, CYFIP1 promotes in the brain the translation repression activity of FMR1, the main causative factor of X-Fragile syndrome, to the extent that haploinsufficiency of Cyfip1 produces fragile X-like phenotypes in mice." (PMID 30936846, 2019). "CYFIP1 protein interacts with FMRP, whose monogenic absence causes fragile X syndrome (FXS)." (PMID 31209152, 2019). "Indeed, alteration of CYFIP1 in PWS-like fragile X syndrome patients was recently reported which provides a molecular basis for the clinical observation." (PMID 18226259, 2008). "In parallel, we discuss how clinical studies of fragile X syndrome or 15q11.2 deletion patients have informed our understanding of FMRP and CYFIP1, and highlight the latest psychiatric genomic findings that continue to implicate FMRP and CYFIP1." (PMID 34883502, 2020). "The protein product of CYFIP1 has been proved to interact with FMRP, the protein coded by the FMR1 gene, which is responsible for the Fragile X syndrome." (PMID 33019446, 2020). "Additionally, previous studies have noted that CYFIP1 haploinsufficiency can generate features of the fragile X syndrome phenotype in mice, while a subgroup of individuals with fragile X syndrome have a Prader-Willi-like phenotype, but no specific cause for these phenotypes is known." (PMID 30909440, 2019). "However, the most compelling candidate in the deleted region is CYFIP1, which codes for a binding partner of FMRP, the protein responsible for fragile X syndrome." (PMID 22346768, 2012).
breast carcinoma (15 papers, 2009 to 2025). "Loss of CYFIP1 expression has been found in a number of human cancers, including breast cancer, colon cancer, lung cancer, bladder cancer, cutaneous squamous cell carcinoma, nasopharyngeal carcinoma, and acute lymphoblastic leukemia." (PMID 33145876, 2021). "We found that GAS7 was associated with CYFIP1 and WAVE2 complex to suppress breast cancer metastasis via blocking CYFIP1 and Rac1 protein interaction, actin polymerization, and β1-integrin/FAK/Src signaling." (PMID 29706651, 2018). "Overall, these results suggest that GAS7 associates with CYFIP1 to perturb the binding of CYFIP1 and active form of Rac1, thus resulting in the inhibition of actin polymerization in breast cancer cells." (PMID 29706651, 2018). "Studies have shown that abnormal expression of CYFIP1 is linked to metastasis in breast cancer, suggesting that m7G modification may regulate distant metastasis by affecting genes such as CYFIP1." (PMID 40747121, 2025). "In breast cancer, GAS7 was associated with CYFIP1 and WAVE2 complex to suppress breast cancer metastasis via blocking CYFIP1 and Rac1 protein interaction, actin polymerization, and β1-integrin/FAK/Src signaling." (PMID 38370374, 2024). "To further figure out the underlying molecular mechanisms, we performed bulk RNA-seq with breast cancer MCF7 cell lines of control, as well as deficient of PIP5K1A, NCKAP1, or CYFIP1." (PMID 39408874, 2024). "Our investigations identified methylation at CYFIP1 as a novel epigenetic biomarker candidate for sporadic breast cancer in the Uruguayan population." (PMID 33145876, 2021). "Among the candidate CpGDMs, we found eight genes with differential methylation previously associated with breast cancer susceptibility and pathology in the G2SBC and COSMIC Databases (AMOTL1, CDCP1, CYFIP1, MAP3K6, MIB2, SDK1, TAL1, and TYROBP)." (PMID 33145876, 2021). "Hypermethylation of CYFIP1 gene (only CpGDM hypermethylated in patients) was observed in patients with breast cancer (P = 2.22 × 10−12), while MAP3K6 and MIB2 gene promoters showed a slight hypomethylation in BCP." (PMID 33145876, 2021). "In order to study CYFIP1 as a candidate sporadic breast cancer biomarker in blood, we evaluated the strength to predict BCP against controls using ROC curves in the validation cohort." (PMID 33145876, 2021). "With the aim to elucidate the possible functional role of our candidate biomarker in breast cancer, we analyzed in silico methylation data of CYFIP1 (cg26568226) in tissue samples from BCP from TCGA Program." (PMID 33145876, 2021). "Specifically, CYFIP1 would play a role in the suppression of breast cancer cell migration/invasion and metastasis, although its suppressive role has been contradicted in other studies." (PMID 33145876, 2021). "To date, CYFIP1 has been shown to inhibit tumor cell invasion in models of colon, lung and breast cancers." (PMID 28410392, 2017). "The protein Wiskott–Aldrich syndrome protein family member 1 (WASF1), which interacts with Cytoplasmic FMR1-interacting protein 1 (CYFIP1), promoting tumour cell movement, invasion, and metabolism, is persistently expressed at high levels in highly invasive prostate and breast cancer cells." (PMID 40243822, 2025). "Through bioinformatics analysis, we found that PIP5K1A, NCKAP1, and CYFIP1 are highly expressed in breast cancer tumors compared with normal tissues, and higher expression of these genes is correlated with a worse prognosis in breast cancer patients." (PMID 39408874, 2024). "Next, we wondered whether CYFIP1 could be contributing to the overall survival of patients with breast cancer." (PMID 33145876, 2021). "In support of our finding that WAVE2 loss is associated with defective epithelial morphogenesis, a recent paper identified that the loss of Cyfip1, a component of the WAVE2 complex that is lost in invasive breast cancers, resulted in aberrant 3D epithelial morphology and defective AJ formation." (PMID 23691243, 2013).
breast carcinoma (continued). "CYFIP1 has been shown to be a novel tyrosine kinase substrate in a breast cancer model." (PMID 20043850, 2009). "In conclusion, we demonstrate that multiple genes, including PIP5K1A, NCKAP1, and CYFIP1, are effective targets for enhancing MHC-I expression in breast cancer cells." (PMID 39408874, 2024). "Here, we propose a regulatory mechanism of breast cancer cell migration in that GAS7b interacts with CYFIP1 protein and prevents recruitment of Rac1-GTP to block actin polymerization, leading to the inhibition of motility of breast cancer cells." (PMID 29706651, 2018). "Furthermore, we verified partially according to KEGG functional enrichment or gene-dependency analysis and figured out multiple genes, including PIP5K1A, NCKAP1, CYFIP1, DIS3, TBP, and EXOC1, as effective gene targets for increasing MHC-I expression in breast cancer." (PMID 39408874, 2024).
epilepsy (15 papers, 2012 to 2025). A brain disorder characterized by episodes of abnormally increased neuronal discharge resulting in transient episodes of sensory or motor neurological dysfunction, or psychic dysfunction. "Mutations in the human CYFIP1 gene have been linked to neurobehavioral disturbances, epilepsy, and psychiatric problems, emerging as risk factor for ASD and SCZ." (PMID 36808152, 2023). "CYFIP1 is a candidate for several clinical conditions impacting cognitive and social abilities, including epilepsy, SZ, intellectual disability, and ASD." (PMID 30936846, 2019). "A subset of genes dysregulated as a result of CYFIP1 knockdown show striking similarity to known epilepsy genes, and as such are strong candidate disease genes." (PMID 26824476, 2016). "Haploinsufficiency of CYFIP1 at 15q11.2, CHRNA7 at 15q13.3, NDE1 at 16p13.11 and PRRT2 at 16p11.2 has been implicated as risk-conferring mechanism for epilepsy and other neurodevelopmental phenotypes." (PMID 25950944, 2015). "Hence, reduced CYFIP1 levels in neural progenitors result in dysregulation of SZ and epilepsy gene networks." (PMID 30936846, 2019). "Epilepsy genes dysregulated in response to CYFIP1 knockdown are involved in synaptic transmission." (PMID 26824476, 2016).
Intellectual disability (14 papers, 2012 to 2025). "The product of CYFIP1 would interact with Fragile X Messenger Ribonucleoprotein, which would cause intellectual disability." (PMID 38784233, 2024). "The CYFIP1 gene also interacts with the protein from the RAC1 (RAS-related c3 botulinum toxin substrate 1; OMIM # 602048) gene, disruption of which causes an autosomal dominant form of intellectual disability." (PMID 30909440, 2019). "Enhanced inhibition upon CYFIP1 deletion could contribute to the intellectual disability and cognitive changes reported in individuals with 15q11.2 microdeletions." (PMID 30784587, 2019). "Both proband 15, a boy affected by TS, OCD, behavioral problems, and mild dysmorphic features, and proband 19, a girl affected by TS, mild intellectual disability, and ODD, presented the recurrent 15q11.2 deletion of about 395 Kb, which includes TUBGCP5, CYFIP1, NIPA1, and NIPA2 genes." (PMID 36833427, 2023).
autism spectrum disorder (11 papers, 2019 to 2025). A spectrum of developmental disorders that includes autism, and Asperger syndrome. "CYFIP1, a protein that interacts with FMRP and regulates protein synthesis and actin dynamics, is overexpressed in Dup15q syndrome as well as autism spectrum disorder (ASD)." (PMID 31198525, 2019).
Angelman syndrome (7 papers, 2008 to 2024). A neurogenetic disorder characterized by severe intellectual deficit and distinct facial dysmorphic features. "While CYFIP1 heterozygosity has been rigorously studied due to its loss in 15q11.2 deletion, Prader-Willi and Angelman syndrome, the effects of CYFIP1 overexpression, as is observed in patients with CYFIP1 duplication, are less well understood." (PMID 31198525, 2019). "The less frequent microdeletion 15q11.2, containing four protein-coding genes (NIPA1, NIPA2, CYFIP1, and TUBGCP5), is associated with Burnside–Butler syndrome (BBS), which partially overlaps with certain neurodevelopmental disorders, including Prader-Willi and Angelman syndrome." (PMID 36553064, 2022). "It is adjacent to the Parder–William/Angelman syndrome imprinting area, and its size is approximately 500 kb, involving four OMIM genes: NIPA1, NIPA2, CYFIP1, and TUBGCP5, which are hot spots in clinical research." (PMID 38172840, 2024).
Anxiety (5 papers, 2012 to 2023). Intense feelings of nervousness, tension, or panic often arise in response to interpersonal stresses. "In this study, we assess how overexpression of the highly conserved human CYFIP1 influences rodent behavior, screening specifically for deficits in social interaction, repetitive behaviors, learning and memory impairments, anxiety, and fear." (PMID 31198525, 2019). "A positive correlation was observed between CYFIP1 mRNA levels and the ADAMS general anxiety (r = 0.36, p = 0.018) and with the ADOS-2 comparison score (r = 0.32, p = 0.0441)." (PMID 37508583, 2023). "The relatively selective increase in OC-like but not anxiety-like behavior following Cyfip1 deletion is consistent with a lack of genetic correlation between marble burying and anxiety and supports marble burying as a repetitive, perseverative-like behavior." (PMID 31324746, 2019). "We also do not observe any increased anxiety or hyperactivity with CYFIP1 overexpression." (PMID 31198525, 2019).
developmental delay (5 papers, 2019 to 2025). "The copy number variation (CNV) of 15q11.2, an emerging and common condition observed during prenatal counseling, is encompassed by four highly conserved and non-imprinted genes—TUBGCP5, CYFIP1, NIPA1, and NIPA2—which are reportedly related to developmental delays or general behavioral problems." (PMID 34680874, 2021).
Prader-Willi syndrome (5 papers, 2008 to 2023). "Based on the association of Cyfip1 with Prader-Willi syndrome, one hypothesis is that Cyfip1 polymorphisms also affect BED and hyperphagia." (PMID 29324652, 2018). "CYFIP2 is a homolog of CYFIP1 which is one of four paternally-deleted genes in patients with Type I Prader-Willi Syndrome (PWS), a neurodevelopmental disorder whereby 70% of cases involve paternal 15q11-q13 deletion." (PMID 31324746, 2019). "The identification of CYFIP1 in the PWS candidate region may provide a molecular framework for further investigation, particularly in the area of shared autistic behavior between fragile X and Prader-Willi syndromes." (PMID 18226259, 2008).
Obesity (4 papers, 2015 to 2024). Accumulation of substantial excess body fat. "It is noteworthy that there are also case reports of individuals with FXS exhibiting a Prader-Willi phenotype (i.e., hyperphagia and obesity), which was likely caused by reduced cytoplasmic FMRP interacting protein (CYFIP1) expression." (PMID 38908375, 2024). "The findings of a positive correlation of MMP-9 levels with obesity, CYFIP1 mRNA with mood and autistic symptoms, and FMR1 mRNA expression level with better cognitive, language, and adaptive functions indicate potential biomarkers for specific FXS phenotypes." (PMID 37508583, 2023). "To gain insight into the molecular mechanisms associated with PO effects of Cyfip1 deletion on PF intake, we examined transcription of Cyfip1, Cyfip2, and Magel2 - a nearby imprinted gene within the syntenic, canonical PWS region that is implicated in hyperphagia and obesity (Tacer and Potts." (PMID 31324746, 2019).
bladder cancer (3 papers, 2017 to 2022). "CYFIP1, a newly discovered tumor suppressor gene, shows some tumor-suppressive effects in breast, lung, colon, and bladder cancers." (PMID 35620469, 2022).
melanoma (3 papers, 2020 to 2023). A malignant, usually aggressive tumor composed of atypical, neoplastic melanocytes. "As a model system to systematically analyze the molecular consequences of CYFIP2 mutations normally occurring in neurodevelopmental disorders, we focused on B16-F1 mouse melanoma cells, in which the CYFIP1 and CYFIP2 genes were disrupted using CRISPR/Cas9." (PMID 32486060, 2020). "To do this, we employed a B16-F1 melanoma clone that had arisen from our attempts to disrupt Rac1/2/3 genes in the CYFIP1/2 null background." (PMID 32486060, 2020).
psychosis (3 papers, 2013 to 2022). "Our findings suggest that mutations in the CYFIP1 network might explain part of the autistic features observed in FXS patients, which can also suffer from psychosis." (PMID 24050404, 2013). "Other genes and snoRNAs that might play a role in the onset of psychosis are GABRG3, NDN, CYFIP1 and SNORD115." (PMID 35887798, 2022).
acute lymphoblastic leukemia (2 papers, 2021 to 2023). Leukemia with an acute onset, characterized by the presence of lymphoblasts in the bone marrow and the peripheral blood. "However, recent studies have found that CYFIP1 is low expressed in acute lymphoblastic leukemia, which may be a potential biomarker of acute lymphoblastic leukemia." (PMID 37206976, 2023).
Alzheimer disease (2 papers, 2013 to 2016). A progressive, neurodegenerative disease characterized by loss of function and death of nerve cells in several areas of the brain leading to loss of cognitive function such as memory and language. "There appeared to be an upregulation in CYFIP1 levels in severe Alzheimer’s disease hippocampus (t= 3.27,P< 0.01), contrary to the significant downregulation of CYFIP2 expression." (PMID 27524794, 2016). "Unexpectedly, we found a downregulation of CYFIP1 expression by ∼60% in 12-month-old Tg2576 mice (t= −5.49,P< 0.01), instead of an upregulation of CYFIP1 expression observed in post-mortem, severe Alzheimer’s disease hippocampus." (PMID 27524794, 2016). "As CYFIP1 has similar functionsin vitroto CYFIP2, we wanted to know if CYFIP1 could be implicated in mild stages of Alzheimer’s disease." (PMID 27524794, 2016). "Here, we tested this hypothesis by analysing CYFIP2 and CYFIP1 expression in post-mortem Alzheimer’s disease brain tissue." (PMID 27524794, 2016). "We further studied whether CYFIP1 expression is altered in old Tg2576 mice, which model early stages of Alzheimer’s disease." (PMID 27524794, 2016). "In contrast to CYFIP2 expression, the level of CYFIP1 expression is not changed in post-mortem Alzheimer’s disease brain, with the exception that CYFIP1 expression is elevated in severe Alzheimer’s disease hippocampus." (PMID 27524794, 2016). "There was also no change of CYFIP1 expression in STG tissues from patients with severe Alzheimer’s disease (t= −1.15,P= 0.26), as opposed to CYFIP2 reduction seen in severe Alzheimer’s disease STG." (PMID 27524794, 2016).
cutaneous squamous cell carcinoma (2 papers, 2017 to 2021). "CYFIP1 may be a link between loss of differentiation and invasive potential in malignant keratinocytes of cutaneous squamous cell carcinoma." (PMID 28410392, 2017).
Dyscalculia (2 papers, 2021 to 2022). A specific learning disability involving mathematics and arithmetic. "A Copy Number Variant (CNV) scan for psychiatric conditions in the Icelandic population also identified a region in chromosome 15q11.2 between breakpoints 1 and 2 [15q11.2 (BP1-BP2) deletion] in controls with a history of dyslexia and dyscalculia, disrupting GCP5, CYFIP1, NIPA2, and NIPA1." (PMID 35911657, 2022).
obsessive-compulsive disorder (2 papers, 2019 to 2025). A disorder characterized by the presence of persistent and recurrent irrational thoughts (obsessions), resulting in marked anxiety and repetitive excessive behaviors (compulsions) as a way to try to decrease that anxiety. "CYFIP1 stabilizes axon processes and dendritic complexity, while TUBGCP5 has been linked to ADHD and obsessive-compulsive disorder (OCD)." (PMID 40843057, 2025).
squamous cell carcinoma (2 papers, 2017 to 2024). A carcinoma arising from squamous epithelial cells. "CYFIP1 expression was next assessed in cultured normal human keratinocytes (HKCs) and in established human squamous cell carcinoma cell lines derived from skin: SCC12, SCC13 and A431." (PMID 28410392, 2017). "In vitro studies of squamous cell carcinoma (SCC) show that activated Notch1 binds to the CSL sequence in the CYFIP1 gene promoter, upregulating CYFIP1 at both the mRNA and protein levels." (PMID 38685115, 2024).